CXCR4 (C-X-C motif chemokine receptor 4)
Diseases named in the same sentence as CXCR4 in open-access papers (continued):
Sharing a sentence is not in itself a finding about the gene and the disease.
breast carcinoma (continued). "In breast cancer patients it was reported that low serum SDF-1 levels may favor the migration of tumor cells overexpressing CXCR4, promoting the development of distant metastasis." (PMID 29285291, 2017). "NT21MP, a 21-residue peptide derived from the viral macrophage inflammatory protein II, competed effectively with the natural ligand of CXC chemokine receptor 4 (CXCR4), stromal cell-derived factor 1-alpha, to induce apoptosis and inhibit growth in breast cancer." (PMID 28415580, 2017). "Moreover, binding of bone marrow-derived CXCL12 to its receptor CXCR4 can activate Akt, thus promoting breast cancer bone metastasis." (PMID 28356139, 2017). "Besides, DIM lowered the invasive and metastatic potential of breast cancer cells through downregulation of CXCR4 and CXCL12." (PMID 28698459, 2017). "Targeting the SDF-1α–CXCR4 signaling pathway has also been studied in breast cancer treatment." (PMID 28415580, 2017). "Inhibition of the oncogenic EMT process by targeting CXCR4/PDGFRα-mediated pathways using NT21MP may provide a novel therapeutic approach towards breast cancer." (PMID 28415580, 2017). "In addition, BAG3 was found to be positively correlated with CXCR4 expression and unfavorable prognosis in patients with breast cancer." (PMID 28703799, 2017). "In addition, the CXCR4 over-expression in breast cancer cells is thought to be important in driving the metastatic involvement towards organs as bone and lungs that secrete many ligand molecules acting as a chemo-attractant gradient." (PMID 29099748, 2017). "More importantly, CXCR4 expression is a prognostic marker in breast carcinoma." (PMID 29263923, 2017). "This suggests that CXCR4-mediated cell-based therapeutics can be used to treat breast cancer." (PMID 28740515, 2017). "FACS analysis showed that patient-derived breast cancer cells expressed both CXCR4 and CXCR6." (PMID 28649646, 2017). "Utilizing our hydrogel assay system, patient-derived breast cancer cells were treated with a receptor-blocking antagonist directed against CXCR4 alone or in combination with neutralizing antibody directed against CXCL16 and tested for cancer cell migration to brain metastatic CAF aggregates." (PMID 28649646, 2017). "We found that ligand-activated PPARγ downregulated CXCR4 transcriptional activity through the recruitment of the silencing mediator of retinoid and thyroid hormone receptor (SMRT) corepressor onto a newly identified PPAR response element (PPRE) within the CXCR4 promoter in breast cancer cell lines." (PMID 27556298, 2016). "Breast cancer metastasis is known to be mediated in part by the CXCL12/CXCR4 signaling axis." (PMID 27049755, 2016). "It is known that both KLF8 and CXCR4 are aberrantly overexpressed in breast cancer." (PMID 26993780, 2016). "Additionally, SDF-1/CXCR4 signaling in ECs under hypoxic conditions leads to tube formation, adhesion of breast cancer cells to ECs and stimulates transendothelial migration in a HIF-dependent manner." (PMID 27706047, 2016). "The role of chemokine receptors in metastatic organ selectivity was first reported for CXCR4, a receptor that stimulates metastasis of breast cancer and melanoma cells to the lung and lymph node where its ligand, CXCL12 (also known as SDF-1: stromal cell-derived factor 1), is abundant." (PMID 27136535, 2016). "Importantly, CXCR4 is a predictive marker for bone metastasis in breast cancer patients with visceral metastases." (PMID 27706047, 2016). "In contrast, delivery of antimiR-218-5p decreased Wnt activity and the expression of metastasis-related genes, including bone sialoprotein (BSP/IBSP), osteopontin (OPN/SPP1) and CXCR-4, implicating a Wnt/miR-218-5p regulatory network in bone metastatic breast cancer." (PMID 27738322, 2016). "Notably, we reported that HRG-induced activation of P-Rex1/Rac1 and motility via ErbB3 in breast cancer cells is mediated by transactivation of CXCR4, a G-protein-coupled receptor widely involved in metastatic dissemination." (PMID 27351228, 2016).
breast carcinoma (continued). "CXCR4 expression was detected at very low levels in MCF-10A cells in respect with ERα-positive MCF-7 breast cancer cells, while higher CXCR4 levels were observed in ER-negative MDA-MB-231 breast cancer cells, which are well-characterized in terms of their metastatic potential and properties." (PMID 27556298, 2016). "Indeed, in breast cancer cells, CXCR4 expression is downregulated by administration of the TDZ drug BRL as evidenced by reduction of its mRNA and protein levels." (PMID 27556298, 2016). "Overexpression of CXCR4 in primary breast tumors is directly correlated to the degree of lymph node metastasis and poor survival rates in breast cancer patients, which suggest that CXCR4 expression could be used as a prognostic marker." (PMID 26848769, 2016). "Moreover, blocking CXCR4 expression at the mRNA level decreased breast cancer cell invasion in in vitro assays and inhibited metastasis in an animal model." (PMID 27618899, 2016). "CXCR4 is a receptor for chemokine CXCL12 and has recently been linked to breast cancer metastasis." (PMID 26993780, 2016). "Recently it was shown, that CXCR4 signaling regulates breast cancer stem cell activities and thus could be important in tumour formation at the sites of metastases." (PMID 26896000, 2016). "Aberrant high levels of CXCR4 have been found in patient tissues of breast cancer." (PMID 26993780, 2016). "Published data demonstrated the analysis of CXCR4 expression by immunohistochemistry in breast cancer tissue and cells and its clinical significance regarding the localization and expression patterns, emphasizing its distinguished relevance as a prognostic marker." (PMID 26161302, 2015). "Therefore, the detection of many other markers, including CXCR4, allows better evaluation of breast cancer, which can strongly influence the therapy conduct (guidance) and survival among patients." (PMID 26161302, 2015). "We also examined whether TPD7 affected CXCR4 expression related to status of HER2 expression in breast cancer cells." (PMID 25753200, 2015). "But in case of gp120/CXCR4-mediated apoptosis, the signaling pathway seems to be Gαi protein-independent, at least in T-cells, whereas gp120/CXCR4-induced apoptosis of breast cancer cells and hepatocytes depends on Gαi protein involvement." (PMID 26347749, 2015). "Indeed, CXCR4 is overexpressed in metastatic breast cancer cells; consequently it critically mediates the homing process to specific metastatic sites." (PMID 26161302, 2015). "Interestingly, CXCR7 expressing breast cancer cells not only enhanced proliferation of CXCR4 positive breast cancer cells but also supported spontaneous metastasis." (PMID 26091099, 2015). "In summary, here we show that breast cancer cell-derived ANGPTL2 may play important roles in bone metastasis by enhancing responsiveness of breast cancer cells to bone tissue-secreted CXCL12 through up-regulated tumor cell CXCR4 expression." (PMID 25773070, 2015). "This evidence first identified a key function of CXCR4/CXCL12 in metastatic breast cancer." (PMID 27429863, 2015). "Finally, we observed a positive correlation of ANGPTL2 and CXCR4 expression in primary tumor tissues from breast cancer patients." (PMID 25773070, 2015). "Indeed, our previous coculture studies revealed that modulation of the glial-defense by a CXCR4- or WNT-inhibitors or bisphosphonates subsequently reduced the glial-facilitated infiltration of breast cancer cells into the brain parenchyma." (PMID 26299612, 2015). "The chemokine receptor CXCR4 promotes cancer metastasis in breast cancer and melanoma." (PMID 26176534, 2015). "To investigate whether ANGPTL2 increases CXCR4 expression in other breast cancer cells, we generated T47-D lines that constitutively express ANGPTL2 (T47-D/ANGPTL2) and control vector-only lines (T47-D/Control)." (PMID 25773070, 2015). "CXCR4 expression predicts bone metastasis in breast cancer patients." (PMID 26231656, 2015).
breast carcinoma (continued). "Because both proteins were readily identifiable in a significant fraction of human breast cancer samples by immunohistochemistry, CXCR4 may constitute a molecular target for therapy." (PMID 26576337, 2015). "CXCR4 has been reported as a prognostic biomarker in various type of cancer, including gastric cancer, colorectal cancer, esophageal cancer, pancreatic cancer, leukemia/lymphoma, ovarian cancer as well as breast cancer." (PMID 26413813, 2015). "In addition, silencing of CXCR4 in breast cancer cells reportedly reduces metastasis in a mouse xenograft model." (PMID 25773070, 2015). "It was observed that the majority of the breast cancer patients presented higher CXCR4 mRNA relative expression (5.7 fold) than mRNA from normal mammary gland and higher CXCR4 protein expression in the tumor microenvironment compared with tumor adjacent tissue." (PMID 26576337, 2015). "CXCR4 may be overexpressed in breast cancer, and the CXCR4/CXCL12 axis is suggested to be involved in migration and consequently in the invasion and metastasis of breast cancer cells." (PMID 26576337, 2015). "Furthermore, our findings suggest that in bone tissue, CXCL12-activated CXCR4 signaling in breast cancer cells induced by ANGPTL2 also accelerates osteolysis and bone engraftment." (PMID 25773070, 2015). "These evidences supported that CXCR4 is also a direct target gene of GLI1 in breast cancer cells." (PMID 26413813, 2015). "Moreover, CXCR4 in breast cancer activates Janus kinase/signal transducer and activator of transcription (JAK/STAT) pathway, src family, and angiogenesis." (PMID 27429863, 2015). "Thus, the significance of the CXCL12/CXCR4 axis in breast cancer invasion and metastasis has been widely investigated." (PMID 26161302, 2015). "Finally, we found that ANGPTL2 and CXCR4 expression levels within primary tumor tissues from breast cancer patients are positively correlated." (PMID 25773070, 2015). "Finally, ANGPTL2 expression was positively correlated with CXCR4 expression levels in primary tumor tissue from breast cancer patients." (PMID 25773070, 2015). "Given the diversity of findings, the difficulty in evaluating published results from different samples to the complexity of breast cancer subtypes, and the limitations of IHC analysis patterns, it is difficult to draw definitive conclusions about the role of CXCR4 in breast malignancy." (PMID 26161302, 2015). "CXCR4 may be a useful prognostic indicator and a potential therapeutic target in cancer therapies in patients with breast cancer." (PMID 25753200, 2015). "The expression of CXCR4 was investigated in breast cancer cells treated with TPD7." (PMID 25753200, 2015). "However, this study also revealed that breast cancer cells express CXCR4 protein diffusely but at equal levels and that heterogeneity was rarely observed by immunohistochemical staining." (PMID 26161302, 2015). "Overall, these findings suggest that ANGPTL2 may promote breast cancer progression, possibly by activating CXCR4 and MMP-13." (PMID 25773070, 2015). "This hypothesis is supported by recent data which demonstrate that let-7, due to its ability to decrease the levels of HMGA2 resulting in the down regulation of CXCR4, inhibits the formation of breast cancer bone metastases." (PMID 25909161, 2015). "In this regard, assessing the CXCR4 expression as a molecular breast cancer biomarker is highly demanded, and this may be performed with a standardized scoring system." (PMID 26576337, 2015). "Additionally, numerous studies identified that the expression of CXCR4 significantly correlates with metastasis in multiple tumor types, including prostate cancer melanoma, breast cancer and rhabdomyosarcoma." (PMID 26622806, 2015).
breast carcinoma (continued). "Metastases, rather than primary tumours, are responsible for breast cancer deaths, many experimental and clinical studies have demonstrated that SDF-1α/CXCR4 axis play a key role in regulating the directional migration of breast cancer cells to sites of metastasis." (PMID 25753200, 2015). "Additionally, Slit2 blocks cell motility and tumorigenesis by downregulation of CXCR4 in a mammary tumor model." (PMID 26572553, 2015). "In addition, we analysed the expression of genes associated, in human and pet mammary cancers, with stem/progenitor cell survival, self-renewal and tumor aggressiveness, such as EGFR, ER-α and CXCR4." (PMID 25884842, 2015). "In addition, other studies have already shown that inhibition of CXCR4 in vivo inhibits the metastatic process and the migration of breast cancer cells." (PMID 24629239, 2014). "To date, CXCR4 is one of the most common chemokine receptors demonstrated to be overexpressed in human cancers, with overexpression reported in more than 23 cancer types, including breast cancer, ovarian cancer, melanoma and prostate cancer." (PMID 24618817, 2014). "Furthermore, this review shows the new molecular targets in breast cancer: CXCR4, caveolin, miRNA, and FOXP3, as promising candidates for future development of effective and targeted therapies, also with lower toxicity." (PMID 24591761, 2014). "What makes CXCR4 account for the poor prognosis in breast cancer?" (PMID 24475985, 2014). "In addition, the migration of breast cancer cells was inhibited by a CXCR4 antagonist, as well as infiltration to the lungs and bone." (PMID 25202367, 2014). "Information about the prognostic and predictive value of CXCR4 in breast cancer is limited." (PMID 24475985, 2014). "Here, we demonstrate that CXCR4 signalling specifically regulates breast cancer stem cell activities and may therefore be important in tumour formation at the sites of metastases." (PMID 24583601, 2014). "However, a recent study has revealed that chemokine (C-X-C motif) receptor 4 (CXCR4) closely correlates with the incidence, development, treatment and prognosis of breast cancer." (PMID 24959222, 2014). "In some cells it has been shown that CXCR7 and CXCR4 cooperate to mediate signaling and we aimed to investigate whether this is the case in breast cancer cell lines." (PMID 25168820, 2014). "In addition to CXCR4, breast cancer cells express another chemokine receptor, CXCR7, which binds to CXCL12 and introduces a new level of complexity in chemokine-receptor signaling." (PMID 24886617, 2014). "Knockdown of CXCR4 significantly limits the growth of orthotopically transplanted breast cancer cells and prevents primary tumor formation in some mice, and all mice transplanted with CXCR RNA interference (RNAi) cells survived without developing macroscopic metastases." (PMID 24647809, 2014). "Our meta-analysis showed that CXCR4 is an efficient prognostic factor for breast cancer." (PMID 24475985, 2014). "However, other studies have indicated that CXCR4 is highly expressed on cancer stem cells, and its activation maintains a stem cell population in tamoxifen-resistant breast cancer." (PMID 24475985, 2014). "In breast cancer, the activation of both CXCR4/CXCL12 and CCR7/CCL21 may reduce the sensitivity of metastatic cancer cells to anoikis by upregulating antiapoptotic proteins." (PMID 25110692, 2014). "They found that CXCR4 was the most highly expressed chemokine receptor in human breast cancer." (PMID 25237365, 2014). "In addition, a recent study has revealed that CXCR4 is vital for the migration, invasion, treatment and prognosis of breast cancer." (PMID 24959222, 2014). "However, stimulation of the CXCR4 pathway in human primary fluid samples from metastatic breast cancer patients increased both stem cell activity and self-renewal." (PMID 24583601, 2014). "Upregulation of CXCR4 is vital for Her2-mediated metastasis of breast cancer." (PMID 24521094, 2014).
breast carcinoma (continued). "Signalling through CXCR4 is found to specifically regulate self-renewal of malignant stem cells which may account for its role in breast cancer progression and metastasis." (PMID 24583601, 2014). "However, there are insufficient studies to confirm the clinical significance of CXCR4 in breast cancer, and its accurate prognostic value in breast cancer is still unclear, especially in the different molecular types of breast cancer." (PMID 24475985, 2014). "In summary, results of this study demonstrate that among several AHR-active pharmaceuticals, omeprazole exhibits antimetastatic activity for triple-negative MDA-MB-231 breast cancer cells, and CXCR4 is one of the key target genes not only for omeprazole but also for other AHR agonists." (PMID 25011475, 2014). "Given this dichotomy between the physiologic and pathophysiologic functions of CXCR4, we hypothesized the constitutive expression of CXCL12 may play a pivotal role in determining the function of CXCR4 signaling in the human breast cancer." (PMID 24810923, 2014). "Blocking CXCR4/CXCL12-induced signaling can slow down the breast cancer growth and metastasis." (PMID 24810923, 2014). "The chemokine receptor subtype CXCR4 is an attractive target for cancer diagnosis and treatment as it is overexpressed in more than 70% of human solid tumors, including mammary cancer, prostate cancer, B-cell lymphoma, neuroblastoma, melanoma, cervical adenocarcinoma, and glioma." (PMID 24634840, 2014). "Additionally, staining of biopsy tissue for less established biomarkers such as the chemokine receptor 4 (CXCR4) has been shown to correlate with aggressiveness/invasiveness and metastatic potential in breast cancer." (PMID 23326303, 2013). "Moreover, Subik and coworkers recently reported that the ubiquitin E3 ligase WWP1 can negatively regulate cell migration to CXCL12 by limiting CXCR4 degradation to promote breast cancer metastasis to bone." (PMID 23472074, 2013). "Constitutively activated STAT3 has been documented as a key driver of breast cancer growth and metastasis, and we have previously reported that STAT3 knockdown in breast cancer cells diminishes CXCR4 expression and inhibits breast cancer growth and metastases in an in vivo tumor transplant model." (PMID 23484027, 2013). "However, the mechanisms through which CXCR4 contributes to breast cancer cell growth and metastases are poorly understood." (PMID 23484027, 2013). "IL-19 induces the expression of CXCR4 in breast cancer cells." (PMID 23710200, 2013). "CXCR4 expression also corroborates with metastatic properties of breast cancer cells." (PMID 23967403, 2013). "Indeed, CXCR4 has been reported to be a prognostic marker in various types of cancer, such as acute myelogenous leukemia and breast carcinoma." (PMID 23987636, 2013). "In addition, CXCR4 has also been found to be a prognostic marker in various types of cancer, including acute myeloid leukemia, breast cancer, and prostate cancer." (PMID 23936528, 2013). "In breast cancer, CXCR4 promotes metastasis to the lungs, liver, and lymph nodes." (PMID 24259307, 2013). "However, the efficacy of CXCR4 blockade in bone metastatic breast cancer patients will await determination in future clinical studies." (PMID 26237063, 2013). "This form of receptor transactivation has been shown to regulate cell proliferation, migration and invasion in various types of cancer, and our recent data indicate an important role for IGF-1R and CXCR4 transactivation in migration of MDA-MB-231 breast cancer cells." (PMID 23320409, 2013). "Furthermore, another study demonstrates the importance of CXCR4 in promoting invasion through human brain microvascular endothelial cells in breast cancer in vitro." (PMID 24259307, 2013). "Recently, Slit2 was shown to downregulate CXCR4 expression in breast cancer cells." (PMID 23294842, 2013). "Indeed, CXCR4 levels were found to be higher in malignant breast tumors in comparison to those of normal healthy counterparts." (PMID 23967403, 2013).